RYR2 (ryanodine receptor 2)
Diseases named in the same sentence as RYR2 in open-access papers (continued):
Sharing a sentence is not in itself a finding about the gene and the disease.
hypertrophic cardiomyopathy (12 papers, 2018 to 2026). "Recently, another RyR2 mutation discovered in a patient from a genotype-negative Hypertrophic cardiomyopathy (HCM) cohort, P1124L, was structurally and functionally characterized." (PMID 35677449, 2022). "In RyR2 SPRY2, T1107M has been associated with hypertrophic cardiomyopathy as well as CPVT." (PMID 35677449, 2022). "Importantly, this interaction may have clinical relevance to the observed cMyBP-C and RyR2 dysfunction in cardiac pathologies, such as hypertrophic cardiomyopathy." (PMID 29930088, 2018). "Moreover, RYR2 alterations are known to be linked to nonstress‐induced cardiac diseases such as left ventricular noncompaction, LQTS, DCM, torsade de pointes, and hypertrophic cardiomyopathy (HCM)." (PMID 41510139, 2026).
long QT syndrome (12 papers, 2009 to 2025). "Susceptibility genes can be analyzed, such as KCNQ1, KCNH2, KCNE1, and KCNE2, which are involved in long QT syndrome, the RYR2 gene implicated in catecholaminergic polymorphic ventricular tachycardia type 1, or the SCN5A gene associated with Brugada syndrome." (PMID 40361926, 2025). "In this context, susceptibility genes can be analyzed, such as KCNQ1, KCNH2, KCNE1, and KCNE2, which are involved in long QT syndrome, the RYR2 gene implicated in catecholaminergic polymorphic ventricular tachycardia type 1, or the SCN5A gene associated with Brugada syndrome." (PMID 40361926, 2025).
Malignant hyperthermia (12 papers, 2012 to 2025). Malignant hyperthermia is characterized by a rapid increase in temperature to 39-42 degrees C. Malignant hyperthermia may occur in response to either inhalational anesthetics such as halothane, to muscle relaxants such as succinylcholine, or to exercise. "The Repeat12 domain boasts positions for five malignant hyperthermia mutations in RyR1 and two CPVT mutations in RyR2." (PMID 26245150, 2015). "As an example, we have mapped all the mutations in RYR2 that cause CPVT and other cardiac diseases onto RYR1, which can be used to assess novel missense variants found in patients with malignant hyperthermia or central core disease." (PMID 24136861, 2014). "ARVD2 associated RYR2 mutations (p.R176Q, p.L433P, p.N2386I and p.T2504M) locate to two distinct clusters in the cytosolic part of the molecule that correspond to the mutational domains of the skeletal muscle RYR1 channel causing malignant hyperthermia (MH) or central core disease (CCD)." (PMID 24978818, 2014).
polymorphic ventricular tachycardia (12 papers, 2015 to 2025). A ventricular tachycardia that is irregular in rate and rhythm. "For instance, RYR2 is implicated in stress‐induced polymorphic ventricular tachycardia, and interestingly, it was detected in Chinese populations under cold conditions." (PMID 40313212, 2025). "A novel RyR2 mutation, H29D, has recently been identified and is believed to be associated with short-coupled polymorphic ventricular tachycardia at rest." (PMID 26405799, 2015). "Notable examples include RYR2, known for its association with stress‐induced polymorphic ventricular tachycardia and which may be associated with adaptation to high altitude in the Tibetan chickens." (PMID 40313212, 2025). "It was proposed that the H29D mutation causes a 'leaky' channel at low cytosolic Ca2+ concentrations, and that 'leaky' RyR2 may be a mechanism for polymorphic ventricular tachycardia at rest." (PMID 26405799, 2015). "The typical CPVT RyR2 mutations render RyR2 channels more prone to spontaneous Ca2+ release resulting in Ca2+ waves that trigger membrane depolarizations, premature ventricular beats (PVB), and polymorphic ventricular tachycardia (PVT) during physical activity or emotional stress." (PMID 34202968, 2021).
cardiac arrest (11 papers, 2012 to 2026). Cessation of breathing and/or cardiac function. "In this study, we have used hiPSC‐CMs to elucidate the arrhythmogenic mechanism of a nonsense variant of the RYR2 gene detected in a young patient who suffered a cardiac arrest." (PMID 35439358, 2022). "We identified a novel nonsense variant in RYR2 in a young woman who suffered an unexplained cardiac arrest." (PMID 35439358, 2022). "The novel nonsense variant in RYR2, c.14368C>T, p.(Arg4790Ter), was identified in a woman in her fourth decade who suffered a cardiac arrest during sexual intercourse." (PMID 35439358, 2022). "We have recently detected a nonsense variant in RYR2 in a young patient who suffered an unexplained cardiac arrest." (PMID 35439358, 2022). "When the proband was initially diagnosed with CPVT following her cardiac arrest, exons of RyR2 encompassing hot spot mutations and all coding exons of CASQ2 and TRDN were first screened, but no variant was found." (PMID 34202968, 2021). "Here, we present a four‐generation family with a novel RYR2 variant (c.527G > T, p.R176L) identified after cardiac arrests in a mother and daughter." (PMID 31994352, 2020). "Many of the patients with the RYR2 mutation had similar exercise-induced cardiac events (4 syncope, 2 VF, 1 cardiac arrest)." (PMID 26132555, 2015). "In addition, despite no statistical significance, patients with CASQ2 mutations appeared to suffer from a lower rate of cardiac arrest and mortality rate compared to those with RYR2 mutations." (PMID 38053087, 2023). "Using WebGestalt algorithms, in the present case, the combination of MYBPC3, TTN, ACADVL, and RYR2 increased significantly the likelihood of cardiac arrest." (PMID 32101375, 2020). "On the other hand, RyR2 LOF variants have been identified among survivors of cardiac arrest without exhibiting the CPVT phenotype and further regarded as RyR2 Ca2+ release deficiency syndrome (CRDS) via an EAD‐mediated mechanism." (PMID 34709746, 2021).
Cognitive impairment (11 papers, 2014 to 2026). Abnormal cognition is characterized by deficits in thinking, reasoning, or remembering. "As a result, the therapeutic targeting of these leaky RyR2 channels holds significant clinical promise in alleviating the persistent cognitive deficits associated with long COVID‐19." (PMID 40152069, 2025). "Indeed, apart from the arrhythmogenic phenotypes, a significant portion of patients harboring CPVT-linked RyR2 mutations also displayed intellectual disability (ID), cognitive deficits, and other neurodevelopmental disorders." (PMID 35233070, 2022). "A possible explanation is that different CPVT RyR2 mutations may affect the RyR2 channel and thus neuronal function to different extents, in turn resulting in variable degrees of cognitive impairment." (PMID 35233070, 2022). "Leaky RyR2 causes cognitive impairment in a murine model of HD." (PMID 32897880, 2020). "Several animal and human models have shown the increased activity of RyR2 in AD and mild-cognitive-impairment brains and a fivefold increase in RyR2 in the brains of 3xTg-AD mice compared to controls." (PMID 37240413, 2023). "The substitution reverses the inhibitory action of CLIC2 on RyR1 and RyR2, so that the H101Q CLIC2 becomes a strong activator of the ion channels and is associated with seizures, cognitive impairment and learning disabilities." (PMID 38203604, 2023). "For example, the expression of RyR2 was upregulated in patients with mild cognitive impairment and AD." (PMID 34072743, 2021). "S107 treatment of Q175 mice significantly improved the escape latency and the time spent in the target quadrant compared with untreated Q175 mice, suggesting that RyR2 channel leak likely contributes to the cognitive deficits observed in the Q175 mice." (PMID 32897880, 2020). "Recently another paper reported elevated RyR2 mRNAs levels early in mild cognitive impairment derived brains." (PMID 24902695, 2014). "Moreover, we observed a decrease in RyR2 cluster size and reduced CRU organization in AD mice at an age associated with high plaque burden and cognitive deficits." (PMID 42249616, 2026). "In AD patients with mild cognitive impairment, RyR2 expression is increased." (PMID 34072743, 2021). "We also report that oral administration of the general antioxidant NAC, a biological GSH precursor, preserved hippocampus redox potential and protected against the cognitive deficits, the GSH reduction and the RyR2 decrease induced by AβOs injections." (PMID 30574085, 2018).
paroxysmal AF (11 papers, 2018 to 2025). "The miR-106b~25 cluster consists of the highly conserved miR-106b, miR-93, and miR-25 and is downregulated in patients with paroxysmal AF, which is associated with elevated RyR2 expression." (PMID 34638924, 2021). "The post-transcriptional regulation of RyR2 mediated by the miR-106b-25 cluster could be a potential target for future gene therapy, since its loss would promote paroxysmal AF by the potentially arrhythmogenic Ca2+ leakage in the sarcoplasmic reticulum." (PMID 37629037, 2023). "In contrast to the situation in JDP2-overexpressing mice, however, RyR2 expression was increased in human paroxysmal AF." (PMID 40710332, 2025). "SPEG protein levels, and RyR2 S2367 phosphorylation are decreased in atrial biopsies from patients with paroxysmal AF and transgenic RyR2-S2367A mice, in which the site cannot be phosphorylated, exhibited an increased susceptibility to pacing-induced AF." (PMID 34690808, 2021). "Several studies have demonstrated that the level of RyR2 protein is elevated in the atria of patients with paroxysmal AF." (PMID 34638924, 2021). "In RAA tissue of patients with paroxysmal AF, these values were unchanged, with 55.3 ± 2.8% and 89.9 ± 0.8% of RyR2 labeling co-localized with or within 300 nm of α-actinin, respectively." (PMID 33718369, 2021). "However, RYR2 phosphorylation was unaltered in a patient with paroxysmal AF, whereas the RYR2 single-channel open probability was increased." (PMID 30450052, 2018). "Indeed, physiologically observed degrees of RyR2 heterogeneity had a larger impact on SCaEs than differences in total RyR2 expression observed between patients with sinus rhythm and paroxysmal AF." (PMID 30166973, 2018). "Indeed, we have previously shown in paroxysmal AF patients with a similar phenotype that RyR2 and SERCA2a dysfunction can each promote proarrhythmic spontaneous SR Ca2+-release events and that the combination of both factors is significantly more proarrhythmic than each individually." (PMID 30356673, 2018). "In non-AF RAA, there was a mean of 42.44 ± 2.28% of RyR2 clusters aligned with the z-disk, which was not significantly altered in either of the AF patient groups (paroxysmal AF: 45.89 ± 2.45% and persistent AF: 46.60 ± 2.24%)." (PMID 33718369, 2021). "Despite the lack of clarity as to the link between RyR2 cluster size and spontaneous Ca2+ release, we identified that mean RyR2 cluster size was unaltered in either persistent or paroxysmal AF samples, and that all three patient groups showed a highly similar distribution of cluster sizes." (PMID 33718369, 2021). "RyR2 density did not significantly differ between the patient groups (non-AF: 163.6 ± 11.6 a.u., paroxysmal AF: 146.9 ± 17.2 a.u. and persistent AF: 149.4 ± 12.9 a.u.), indicating that RyR2 channel packing is unaltered within clusters in the RAA of AF patients." (PMID 33718369, 2021). "Using this latter imaging technique, we have assessed the nanoscale morphology and organization of RyR2 clusters in RAA tissue from patients with persistent and paroxysmal AF, or without AF." (PMID 33718369, 2021).
arrhythmogenic right ventricular dysplasia type 2 (10 papers, 2013 to 2025). "Catecholaminergic polymorphic ventricular tachycardia type 1 (CPVT1) is known to arise from mutations to RyR2." (PMID 36742199, 2022).
Glucose intolerance (10 papers, 2016 to 2025). Glucose intolerance (GI) can be defined as dysglycemia that comprises both prediabetes and diabetes. "CPVT patients with RYR2 mutations, including RYR2-R2474S and RYR2-N2386I, have been found to have glucose intolerance." (PMID 40422193, 2025). "Certain missense mutations in the RYR2 gene in this hotspot are associated with complete penetrance for glucose intolerance." (PMID 40422193, 2025). "Second, the variant is located in a hotspot for CPVT mutations in RYR2 that is associated with complete penetrance for glucose intolerance." (PMID 38444585, 2024). "RyR2-mediated Ca2+ release contributes to glucose-mediated insulin secretion and pathogenic RyR2 mutations cause glucose intolerance in humans and mice." (PMID 38444585, 2024). "Genetic studies in humans revealed that patients with mutations in RyR2 associated with severe arrhythmias are also prone to glucose intolerance." (PMID 37141277, 2023). "A mutation in RyR2 mimicking CaMKII phosphorylation leads to basal hyperinsulinemia and glucose intolerance, both ascribed to increased leak of Ca2+ from the ER via RyR212." (PMID 35562179, 2022). "They found that CPVT RyR2 mutated patients as well as transgenic CPVT mice exhibited glucose intolerance and impaired glucose homeostasis." (PMID 34725342, 2021). "Whole-exome sequencing has identified an atypical missense variant in the RYR2 gene that co-segregated with T2DM in a family study, associated with glucose intolerance." (PMID 40422193, 2025). "We found that murine models of human CPVT with mutant leaky RyR2 also quite unexpectedly displayed glucose intolerance secondary to impaired insulin secretion due to leaky RyR2 channels in their pancreatic β cells." (PMID 36647824, 2023). "Mice with chronic activation of CAMK2 in beta cells developed glucose intolerance and abnormal insulin secretion through a ryanodine receptor 2 (Ryr2) dependent mechanism." (PMID 28777829, 2017).
chronic heart failure (9 papers, 2010 to 2023). "However, in chronic heart failure, intracellular Ca2+ overload and Ca2+ depletion in SR are due not only to Ca2+ leakage from failing RyR2 but also to decreased Ca2+ uptake, which is caused by down-regulation of sarcoma/endoplasmic reticulum Ca2+-ATPase and decreased PLB phosphorylation." (PMID 25614983, 2015).
colon cancer (9 papers, 2020 to 2025). "Studies have shown that RYR2, a member of the ryanodine receptor family, has been linked to the development and progression of various cancers, including lung, liver, and colon cancer." (PMID 39872045, 2024). "We analyzed the changes in SLC7A7 and gene mutations, acquisitions, and deletions in colon cancer, the difference in APC, TTN, KRAS, SYNE1, RYR2, and LRP1 mutations was statistically significant." (PMID 39730571, 2024).
lung cancer (9 papers, 2019 to 2024). A malignant neoplasm involving the lung. "What is more, other mutated genes, such as TTN, MUC16, and RYR2, all previously reported to regulate tumorigenesis and chemoresistance in lung cancer, were the most common mutations in both cohorts, indicating a lack of significant immune infiltration." (PMID 36246963, 2022). "Further studies are needed to characterize the mechanism underlying mutation of RYR2 in lung cancer and to explore potential relationships between RYR2 and high TMB." (PMID 31480292, 2019). "In nonsmall cell lung cancer, RYR2 mutation may prolong survival via downregulation of DKK1 and upregulation." (PMID 35975176, 2022). "This is a possible underlying mechanism by which the association between RYR2 and lung cancer could arise." (PMID 31480292, 2019). "Therefore, mutations in RYR2 may result in the alteration of airway smooth muscle and asthma, which is a possible risk factor for lung cancer." (PMID 31480292, 2019). "Indeed, the alterations found in these genes such as RYR2, NOTCH1 and DMBT1 have strong association with high tumor burden and tumorigenesis, possibly resulting in a worse prognosis in lung cancer patients." (PMID 34336686, 2021).
sudden cardiac arrest (9 papers, 2015 to 2026). Unexpected rapid natural death due to cardiovascular collapse within one hour of initial symptoms. "The patient had experienced sudden cardiac arrest at the age of 24, where the RyR2 gene mutation was confirmed, leading to the initiation of beta-blocker therapy." (PMID 40575238, 2025). "Among three isoforms that encode RyR genes (RYR), RYR2 is expressed predominantly in cardiac muscle, and it has been reported to be associated with cardiac diseases such as arrhythmias and sudden cardiac death (SCD)." (PMID 38034995, 2023). "Here, we report a case of CPVT in a patient with RYR2 gene mutation, causing sudden cardiac arrest." (PMID 33763313, 2021). "In addition, VA reported in patients with KCNJ2 mutations have been described as milder than in RYR2 mutated patient, especially rarely leading to syncope or sudden cardiac arrest." (PMID 34899860, 2021). "The protein “ryanodine receptor 2”, in which this CSI is found, is a calcium release channel that is present in the heart and brain and mutations in this gene have been linked with leaky channels that can lead to sudden cardiac arrest and seizures." (PMID 35205335, 2022).
Central core disease (8 papers, 2013 to 2022). Central core disease (CCD) is an inherited neuromuscular disorder characterised by central cores on muscle biopsy and clinical features of a congenital myopathy. "An isoform-specific effect on RyR structure was revealed by evaluating the effect of the RyR2-R176Q mutant involved in CPVT and ARVD2, and its homologous the skeletal muscle RyR1-R163C, implicated in malignant hyperthermia (MH) and central core disease." (PMID 34725342, 2021).
Hyperglycemia (8 papers, 2014 to 2025). An increased concentration of glucose in the blood. "Secondly, the ROS overproduction caused by hyperglycemia triggers redox modifications and malfunction of ion channels in cardiomyocytes, e.g. the type 2 ryanodine receptor (RyR2) on the endoplasmic reticulum (ER)." (PMID 29079813, 2017). "The Zn2+-mediated reduction of phosphorylated RyR2 and consequent cardiomyocyte relaxation were more evident in rat cardiomyocytes upon hyperglycemia condition." (PMID 35047109, 2022). "On the other hand, experiments in vitro revealed that during acute hyperglycemia, RyR2 activity can also be altered." (PMID 32038301, 2019). "CaMKII senses intracellular calcium (Ca2+) changes, oxidation status, and hyperglycemia to phosphorylate substrates that regulate Ca2+-sensitive proteins, such as L-type Ca2+ channels, phospholamban, and cardiac ryanodine receptors (RyR2)." (PMID 24672485, 2014). "This could be explained considering that RyR2 phosphorylation was found enhanced in pathological conditions like hyperglycemia and diabetes." (PMID 35047109, 2022). "In addition, hyperglycemia-induced formation of advanced glycation end products on RYR2 and SERCa2a may also contribute." (PMID 40149735, 2025). "Incubation of cardiomyocytes with 10 μM ZnCl2 exerted hyperphosphorylation in RyR2 as well as higher phosphorphorylations in both PKA and CaMKII in a concentration-dependent manner, similar to hyperglycemia." (PMID 24693334, 2014).